HTR2A (5-hydroxytryptamine receptor 2A)
Description:
G protein-coupled receptor for 5-hydroxytryptamine (serotonin). Also functions as a receptor for various drugs and psychoactive substances, including mescaline, psilocybin, 1-(2,5-dimethoxy-4-iodophenyl)-2-aminopropane (DOI) and lysergic acid diethylamide (LSD). Ligand binding causes a conformation change that triggers signaling via guanine nucleotide-binding proteins (G proteins) and modulates the activity of downstream effectors. HTR2A is coupled to G(q)/G(11) G alpha proteins and activates phospholipase C-beta, releasing diacylglycerol (DAG) and inositol 1,4,5-trisphosphate (IP3) second messengers that modulate the activity of phosphatidylinositol 3-kinase and promote the release of Ca(2+) ions from intracellular stores, respectively. Beta-arrestin family members inhibit signaling via G proteins and mediate activation of alternative signaling pathways. Affects neural activity, perception, cognition and mood. Plays a role in the regulation of behavior, including responses to anxiogenic situations and psychoactive substances. Plays a role in intestinal smooth muscle contraction, and may play a role in arterial vasoconstriction (By similarity). (Microbial infection) Acts as a receptor for human JC polyomavirus/JCPyV.
Synonyms: HTR2; 5-HT2A
Tractability: Small molecule: an approved drug acts on it; a structure with a bound ligand is known; a high-quality ligand is known; it belongs to a druggable protein family. Antibody: UniProt places it where antibodies can reach, with high confidence; its Gene Ontology location is reachable by antibodies, with high confidence; UniProt predicts a signal peptide or a membrane-spanning region. PROTAC: a small molecule that binds it is known.
Target class: Monoamine receptor; Family A G protein-coupled receptor; Small molecule receptor (family A GPCR); Serotonin receptor; Membrane receptor
Chemical probes: NBOH-2C-CN (high quality)
Safety:
Unwanted effects reported when the protein is acted on. In parentheses: how it was acted on, where the effect was seen, and who reports it.
hallucinations (Lynch et al. (2017): activation, acute dosing, nervous system, cardiovascular, blood; Bowes et al. (2012): activation, cardiovascular system, central nervous system)
platelet aggregation (Lynch et al. (2017): activation, acute dosing, nervous system, cardiovascular, blood; Bowes et al. (2012): activation, cardiovascular system, central nervous system)
agitation (activation, acute dosing; nervous system, cardiovascular, blood; source: Lynch et al. (2017))
decreased body temperature (inhibition, acute dosing; nervous system, cardiovascular, blood; source: Lynch et al. (2017))
decreased inflammation (inhibition, acute dosing; nervous system, cardiovascular, blood; source: Lynch et al. (2017))
decreased memory (activation, acute dosing; nervous system, cardiovascular, blood; source: Lynch et al. (2017))
decreased pain (inhibition, acute dosing; nervous system, cardiovascular, blood; source: Lynch et al. (2017))
decreased platelet aggregation (inhibition, acute dosing; nervous system, cardiovascular, blood; source: Lynch et al. (2017))
drug abuse/dependence (activation, acute dosing; nervous system, cardiovascular, blood; source: Lynch et al. (2017))
hyperreflexia (activation, acute dosing; nervous system, cardiovascular, blood; source: Lynch et al. (2017))
hypervigilance (activation, acute dosing; nervous system, cardiovascular, blood; source: Lynch et al. (2017))
increased blood pressure (activation, acute dosing; nervous system, cardiovascular, blood; source: Lynch et al. (2017))
increased body temperature (activation, acute dosing; nervous system, cardiovascular, blood; source: Lynch et al. (2017))
increased heart rate (activation, acute dosing; nervous system, cardiovascular, blood; source: Lynch et al. (2017))
increased pain (activation, acute dosing; nervous system, cardiovascular, blood; source: Lynch et al. (2017))
increased pupil diameter (activation, acute dosing; nervous system, cardiovascular, blood; source: Lynch et al. (2017))
increased sleep (inhibition, acute dosing; nervous system, cardiovascular, blood; source: Lynch et al. (2017))
myoclonus (activation, acute dosing; nervous system, cardiovascular, blood; source: Lynch et al. (2017))
potential memory impairments (activation; cardiovascular system, central nervous system; source: Bowes et al. (2012))
psychosis (activation, acute dosing; nervous system, cardiovascular, blood; source: Lynch et al. (2017))
schizophrenia (activation; cardiovascular system, central nervous system; source: Bowes et al. (2012))
serotonin syndrome (activation; cardiovascular system, central nervous system; source: Bowes et al. (2012))
smooth muscle contraction (activation; cardiovascular system, central nervous system; source: Bowes et al. (2012))
stereotypy (activation, acute dosing; nervous system, cardiovascular, blood; source: Lynch et al. (2017))
sweating (activation, acute dosing; nervous system, cardiovascular, blood; source: Lynch et al. (2017))
adverse cognitive effects (source: ClinPGx)
adverse cognitive effects and sexual dysfunctions (source: ClinPGx)
adverse drug reactions (source: ClinPGx)
adverse events (source: ClinPGx)
cardiovascular adverse events (source: ClinPGx)
and 12 more effects
Gene: Protein-coding gene on chromosome 13 (46,831,546 to 46,897,076, reverse strand). Ensembl gene ENSG00000102468.
Subcellular location: Cell membrane; Cell projection, dendrite; Cell projection, axon; Cytoplasmic vesicle; Membrane, caveola; Presynapse
Pathways (Reactome):
Signal Transduction: G alpha (q) signalling events; Serotonin receptors
Gene Ontology:
Molecular function: 1-(4-iodo-2,5-dimethoxyphenyl)propan-2-amine binding; G protein-coupled serotonin receptor activity; Gq/11-coupled serotonin receptor activity; identical protein binding; protein binding; serotonin binding; neurotransmitter receptor activity; G protein-coupled receptor activity; protein tyrosine kinase activator activity; protein-containing complex binding
Biological process: G protein-coupled serotonin receptor signaling pathway; intracellular calcium ion homeostasis; phospholipase C-activating serotonin receptor signaling pathway; positive regulation of ERK1 and ERK2 cascade; positive regulation of phosphatidylinositol biosynthetic process; release of sequestered calcium ion into cytosol; response to xenobiotic stimulus; chemical synaptic transmission; G protein-coupled receptor signaling pathway, coupled to cyclic nucleotide second messenger; serotonin receptor signaling pathway; artery smooth muscle contraction; behavioral response to cocaine; detection of mechanical stimulus involved in sensory perception of pain; detection of temperature stimulus involved in sensory perception of pain; G protein-coupled receptor signaling pathway; memory; negative regulation of potassium ion transport; negative regulation of synaptic transmission, glutamatergic; positive regulation of cell population proliferation; positive regulation of cytokine production involved in immune response; positive regulation of cytosolic calcium ion concentration; positive regulation of DNA biosynthetic process; positive regulation of execution phase of apoptosis; positive regulation of heat generation; positive regulation of inflammatory response; and 10 more
Cellular component: G protein-coupled serotonin receptor complex; plasma membrane; cytoplasmic vesicle; dendrite; presynapse; axon; caveola; cell body fiber; dendritic shaft; glutamatergic synapse; membrane; neurofilament; neuronal cell body; postsynaptic membrane; presynaptic membrane
Genetic constraint (gnomAD): Loss-of-function variants: 14 observed, 34.65 expected, observed/expected ratio (o/e) 0.4, 90% interval 0.27 to 0.63. The upper end of that interval is the gene's LOEUF score, 0.63, which puts it in group 2 of 6, group 1 being the genes least tolerant of losing a copy. Missense variants: 442 observed, 603.2 expected, observed/expected ratio (o/e) 0.73, 90% interval 0.68 to 0.79. Synonymous variants: 209 observed, 238.02 expected, observed/expected ratio (o/e) 0.88, 90% interval 0.78 to 0.99.
Homologues: Orthologues: chimpanzee HTR2A (99% identical), macaque HTR2A (99% identical), pig HTR2A (96% identical), rabbit HTR2A (93% identical), guinea pig HTR2A (92% identical), mouse Htr2a (92% identical), rat Htr2a (91% identical), tropical clawed frog htr2a (72% identical), zebrafish htr2aa (56% identical), zebrafish htr2ab (56% identical), Drosophila melanogaster 5-HT2A (33% identical), Caenorhabditis elegans ser-6 (16% identical). Paralogues in human: HTR2C (48% identical), HTR2B (42% identical), HTR7 (25% identical), HTR1F (23% identical), HTR1E (23% identical), HTR1B (22% identical), HTR6 (22% identical), HTR5A (20% identical).
Diseases named in the same sentence as HTR2A in open-access papers:
HTR2A is named in the same sentence as 193 diseases in open-access papers, as found by Europe PMC text mining. Sharing a sentence is not in itself a finding about the gene and the disease. The quoted sentences say what the papers report.
schizophrenia (116 papers, 2008 to 2025). A major psychotic disorder characterized by abnormalities in the perception or expression of reality. "TENM1 (MO, NY) is associated with neural development and stress‐induced behaviour while HTR2A (NY) is a serotonin receptor associated with major depressive disorder, obsessive‐compulsive disorder, and schizophrenia." (PMID 41208600, 2025). "Polymorphisms in HTR2A have been associated with neuropsychiatric disorders including impulsive behaviour and schizophrenia in humans." (PMID 37531334, 2023). "Polymorphisms in HTR2A have been associated with neuropsychiatric disorders including impulsive behaviour and schizophrenia." (PMID 37531334, 2023). "The 5-hydroxytryptamine receptor 2A (HTR2A) gene polymorphism was implicated to play a role in the pathogenesis of schizophrenia." (PMID 36313375, 2022). "Many of these target genes, such as RELN, DRD1, VSNL1, and HTR2A, with known function in neural connectivity, have already been associated with the development of schizophrenia." (PMID 32764320, 2020). "We found that some connected drugs such as minaprine and thioridazine both target serotonin receptor 2A (HTR2A), a protein associated with the susceptibility to schizophrenia and obsessive-compulsive disorder (right)." (PMID 31852840, 2019). "Based on pharmacological and expression studies, results suggest that the downregulated HTR2A mRNA expression and reduction of receptor density or activity are associated with schizophrenia." (PMID 28054990, 2017). "Although such inconsistency remains to be clarified, these studies suggest an association between the dysregulation of HTR2A mRNA expression and schizophrenia." (PMID 28054990, 2017). "In this study, we examine HTR2A expression and methylation and the interaction with HTR2A polymorphisms to identify their biological significance in schizophrenia." (PMID 28054990, 2017). "Amongst the schizophrenia-susceptibility genes with the most prominent TTTPs were those with established synaptic functions, including Rgs4, Snap25, Kalrn, Htr2a and Nrg1." (PMID 28893375, 2017). "Serotonin receptor 2A (HTR2A) is an important signalling factor implicated in cognitive functions and known to be associated with schizophrenia." (PMID 28054990, 2017). "DRD1, DRD2, and HTR2A have been implicated as drug targets in schizophrenia." (PMID 36671883, 2022). "The HTR2A gene codes for a serotonin receptor and is associated with behavioral traits, schizophrenia and depression, KCNAB3 encodes a subunit of a voltage-sensitive potassium channel, and SPNS1 codes for the Spinster-1 protein implicated in apoptosis in the Drosophila central nervous system." (PMID 26607552, 2015). "An example is the 5-hydroxytryptamine receptor 2A (5HT2A) genomic variant (T102C) that increases the methylation and decreases expression of the 5HT2A and is hypothesized to be involved in the expression of the schizophrenia phenotype." (PMID 32650713, 2020). "In conclusion, we report that there is an association between schizophrenia and three separate factors: reduced HTR2A mRNA expression, hypermethylation of HTR2A promoter CpG sites (cg5, cg7 and cg10) and genetic association with HTR2A genotypes for rs6314 and rs6313." (PMID 28054990, 2017). "Htr2a antagonists, such as atypical antipsychotics (e.g., clozapine and risperidone), are currently used in treating schizophrenia and other psychiatric disorders." (PMID 39569210, 2024). "The objective of this study was to explore the correlation between DRD2, HTR2A, SLC6A4, CYP1A2, and ABCB1 polymorphisms and clozapine response in 100 patients with Treatment-Resistant Schizophrenia." (PMID 38540209, 2024). "In various cancer types, schizophrenia-related genes (HTR2A, COMT, and PRODH) have different expression patterns, and the direction of down-regulation varies." (PMID 37564635, 2023).
schizophrenia (continued). "According to the results of our investigation, the prognostic level is closely correlated with the variations in the expression of the schizophrenia-related genes HTR2A, COMT, and PRODH in various malignancies." (PMID 37564635, 2023). "HTR2A encodes 5-HT2A receptors, which are associated with major depressive disorder, schizophrenia, and suicidality." (PMID 34987393, 2021). "Studies have shown that a reduction in the serotonin 2A receptor (HTR2A), as well as HTR7, is implicated in the pathogenesis of schizophrenia." (PMID 34287335, 2021). "The association with schizophrenia was found for DRD3 rs6280 (p = 0.05) and HTR2A rs7322347 (p = 0.0013)." (PMID 34025476, 2021). "This study aimed to examine molecular associations of HTR1A, HTR1B, HTR2A, HTR2C and HTR6 gene polymorphisms with acute EPS in 229 male schizophrenia patients, following two weeks of haloperidol monotherapy." (PMID 32231051, 2020). "The present paper describes the results of an association study of in the end 24 polymorphic variants of HTR1A, HTR1B, HTR2A, HTR2C, HTR3A, HTR3B, and HTR6 genes with TD and two of its subtypes in 449 patients with schizophrenia." (PMID 32390801, 2020). "There was a 14% reduction in HTR2A mRNA expression in patients with schizophrenia compared to controls (F-value of 8.564 and p-value of 0.006)." (PMID 28054990, 2017). "In this study, we investigated the role of HTR2A in schizophrenia by examining rs6314 and rs6313 genotype, DNA methylation, and the expression of HTR2A mRNA in prefrontal cortex samples of schizophrenia patients." (PMID 28054990, 2017). "Some studies have reported that HTR2A expression is decreased in the brain of patients with schizophrenia and in those who have committed suicide." (PMID 24959950, 2014). "Studies have reported hypomethylation of genes like HTR2A, dysregulation of DNA methylation machinery enzymes, increased methylation of the 5HTR1A promoter, and genome-wide differentially methylated regions in individuals with schizophrenia." (PMID 39908289, 2025). "In addition to HTR1B, other 5-HT receptors, including HTR1A, HTR2A, HTR3, HTR4, and HTR6 are associated with schizophrenia." (PMID 37990254, 2023). "Additionally, our results also revealed a decrease in HTR2A expression in the PFC of individuals with schizophrenia, which is in line with a meta-analysis of postmortem study." (PMID 37990254, 2023). "Importantly, the analysis of DEGs revealed an elevated level of HTR1B in the prefrontal cortex (PFC) (BA46) of individuals with schizophrenia compared to healthy controls (p = 0.034), while the expression of HTR2A was significantly decreased (p = 0.005)." (PMID 37990254, 2023). "However, we did not observe any differences in the mRNA expression of HTR1A and HTR2A in schizophrenia, consistent with the findings of Wysokinski and colleagues." (PMID 37990254, 2023). "Furthermore, DNA methylation of HTR2A is capable of reducing HTR2A expression to facilitate cognitive dysfunction during schizophrenia development." (PMID 35710537, 2022). "HTR2A mRNA levels were reduced by 14% (p = 0.006) in schizophrenia compared to controls." (PMID 28054990, 2017). "The reduced expression of HTR2A mRNA in schizophrenia patients may be mainly attributed to DNA methylation of CpG sites within the promoter-exon I region, and possibly influenced by other underlying factors." (PMID 28054990, 2017). "Overall, this evidence strongly suggests a role for HTR2A in the pathogenesis of schizophrenia." (PMID 28054990, 2017). "HTR2A and DRD3 are listed as risk candidate genes for schizophrenia in ClinVar." (PMID 25522158, 2014). "The complexes searched against CORUM revealed that the 2AR-mGluR2 complex involved in altered cortical process might be potential target for treatment of schizophrenia due to interaction with HTR2A (2AR) and metabotropic glutamate receptors (mGluR)." (PMID 25522158, 2014).
schizophrenia (continued). "HTR2A antagonism contributes to the efficacy of medicines used to treat schizophrenia to the extent that it may be a defining feature of the atypical antipsychotic medicines." (PMID 21829518, 2011). "In our profiling assay, we found that spironolactone also inhibits HTR2A, and antagonists to HTR2A are frequently used for the treatment of schizophrenia, suggesting that such a polypharmacological profile may be beneficial for alleviating symptoms in schizophrenic patients." (PMID 38303712, 2024). "Therefore, epigenetic HTR2A regulation may affect brain function, which contributes to the development of schizophrenia." (PMID 28054990, 2017). "However, it is controversial whether there are changes in HTR2A expression or binding in schizophrenia." (PMID 21829518, 2011). "A set of 29 SNPs of genes of serotonin receptors HTR1A, HTR1B, HTR2A, HTR2C, HTR3A, HTR3B, and HTR6 was studied in a population of 449 Caucasians (226 females and 223 males) with verified clinical diagnosis of schizophrenia (according to ICD-10: F20)." (PMID 32390801, 2020). "Schizophrenia and OCD share common genes, including SLC6A4, BDNF, HTR2A, and DRD2." (PMID 39219434, 2025). "We compared the HTR2A mRNA expression between C/C genotypes and C/T genotypes for all samples, i.e., schizophrenia and control samples were pooled (there were no T/T genotypes present in our sample for rs6314)." (PMID 28054990, 2017).